IL11 (interleukin 11)
Diseases named in the same sentence as IL11 in open-access papers (continued):
Sharing a sentence is not in itself a finding about the gene and the disease.
osteoarthritis (12 papers, 2018 to 2025). A noninflammatory degenerative joint disease occurring chiefly in older persons, characterized by degeneration of the articular cartilage, hypertrophy of bone at the margins and changes in the synovial membrane. "In the context of joint disease, its role is becoming clearer; IL-11 and its receptor are upregulated in the synovium of patients with osteoarthritis and rheumatoid arthritis, which are implicated in promoting inflammation and tissue degradation." (PMID 40951163, 2025). "One of the SNPs was localized to the coding region of IL11, a gene previously implicated in the development of osteoarthritis." (PMID 37156767, 2023). "In humans, mutations of IL-11 and the receptor IL-11RA genes are associated with height reduction, osteoarthritis, and craniosynostosis." (PMID 37199584, 2023). "The fourth locus on chromosome 19 occurs within the coding region of IL11 and this signal colocalizes with several bone-related traits and is a known risk factor for developing osteoarthritis." (PMID 37156767, 2023). "IL11 has been linked with photoaging-induced loss of facial subcutaneous fat and SNPs at the IL11 locus are associated with diseases of aging (e.g. osteoarthritis and menopause)." (PMID 38054591, 2023). "Genetic variants in IL-11 with mutation p.R112H are associated with osteoarthritis and a reduction in adult height." (PMID 37199584, 2023). "The results showed that IL-11 is associated with an increased risk of osteoarthritis and disease progression, and its expression is upregulated in osteoarthritic tissue." (PMID 37199584, 2023). "LOF + MIS variants in ADAMTS6, SPRY2 and COLGALT2 are protective against osteoarthritis, whereas aggregation of these variants in ADAMTSL3, VIT, IL11 and THBS3 confer risk of osteoarthritis." (PMID 40205036, 2025). "For IL11, traits include reproductive span/menopause, height and osteoarthritis, although the directionality of effect of the SNPs remains to be resolved." (PMID 38054591, 2023). "Human GWASs have linked a missense variant in IL11, assumed LOF, with reduced height and there are further GWAS associations at the locus for osteoarthritis (OA), where the rare variants are linked with greater disease." (PMID 38054591, 2023). "We assessed IL-11 expression regulation and the IL-11/IL-6 ratio in osteoarthritis (OA) to better guide clinical therapeutic decision-making." (PMID 30197757, 2018). "The overall direction of genetic colocalization and phenotypic correlations are consistent, with exception of IL11 and POLD3/CHRL2 variants, where colocalization is anti-correlated with osteoarthritis, while phenotypically we see a positive correlation between DISH and OA." (PMID 37156767, 2023). "We first sought to establish a direct link between IL-11 levels, TGF-β1, and the histological severity of synovial fibrosis in a cohort of patients undergoing TKA for advanced osteoarthritis." (PMID 40951163, 2025). "Treatment with BAC protects against IL-1β-induced inflammation in chondrocytes by elevating the expression of IL-11 through activating AP-1 transcriptional activity, indicating the therapeutic potential of BAC in patients with osteoarthritis." (PMID 38983788, 2024).
renal fibrosis (12 papers, 2021 to 2025). A final common manifestation of a wide variety of chronic kidney diseases characterized by glomerulosclerosis and tubulointerstitial fibrosis. "The data presented here demonstrate for the first time that IL11 acts via the Asc-inflammasome to induce placental and renal fibrosis, with loss of Asc preventing IL11 induced fibrosis in the placenta and kidney." (PMID 37292200, 2023). "In vivo, administration of dimethylaminomicheliolide, a pro-drug of MCL, reduced unilateral ureteric obstruction–induced renal fibrosis that was associated with lesser pEMT and a reduction in IL-11–related pathologies." (PMID 37816442, 2023). "The process of crystal deposition can cause kidney damage and renal fibrosis, in which IL11 and its receptor may play a crucial role." (PMID 37480086, 2023). "HG/M1-ftv induce renal interstitial fibrosis in diabetic mice, while FTV inhibition or targeting FTV IL11- alleviates renal interstitial fibrosis, suggesting that the HG/M1-ftvIL11 pathway may be a novel mechanism underlying renal fibrosis in diabetic nephropathy." (PMID 37853428, 2023). "In our SNx obese model, this cytokine could be linked to the worsened CKD and renal fibrosis, as IL11 release in the circulation by adipose tissue can stimulate renal epithelial cell mesenchymal transition and dysfunction, as has been previously demonstrated in cultured cells." (PMID 37571269, 2023). "MCL has recently been shown to have anti-inflammatory properties, on IL-11–related pathologies in models of renal fibrosis and failure." (PMID 37816442, 2023). "Here we present the first evidence that IL11 drives activation of the ASC/NLRP3 inflammasomes, causing villus pyroptosis, placental and renal fibrosis, and the maternal syndrome of preeclampsia, including chronic post-natal hypertension, in mice." (PMID 37292200, 2023). "At that time, data highlighted that IL-11–induced renal fibrosis and dysfunction were ERK related and mediated primarily via its activity in renal fibroblasts, and no connection to RTECs or pEMT was made." (PMID 37816442, 2023). "In acute kidney injury, anti-TGFβ reduces renal fibrosis but exacerbates inflammation and tubule damage whereas anti-IL11 reduces all pathologies." (PMID 36470928, 2022). "We recently identified interleukin 11 (IL11) as a pro-fibrotic factor in fibroblasts and showed that IL11 contributes to renal fibrosis in a mouse model of AKI15 and renal failure in genetically-driven glomerular disease." (PMID 36470928, 2022). "Based on that, this study was designed to identify the potential effects of osthole on IL-11/ERK1/2 signaling pathway in renal fibrosis." (PMID 34054526, 2021). "Considering the critical role of IL-11, an important downstream effector of TGF-β1 signaling, in the progression of renal fibrosis, thus the key molecules of IL-11/ERK1/2 axis were examined." (PMID 34054526, 2021). "It was observed that IL-11/ERK1/2 signaling in renal fibrosis model was significantly upregulated, which was consistent with reported previously." (PMID 34054526, 2021). "Osthole can inhibit the translation of fibrosis proteins by suppressing activated IL-11/ERK1/2 signaling in renal fibrosis, eventually contributing to the amelioration of fibrosis." (PMID 34054526, 2021). "Studies in mouse models have shown that anti-IL-11 treatments can prevent renal fibrosis in both AKI and CKD, which may represent a novel therapeutic avenue." (PMID 39678250, 2024). "Additionally, an anti‐IL‐11 antibody has been evaluated in preclinical studies for liver and renal fibrosis among other fibrotic and inflammatory conditions." (PMID 38023717, 2023). "Taken together, these findings suggested that the regulation of IL-11/ERK1/2 axis may be a promising strategy for combating renal fibrosis." (PMID 34054526, 2021). "Firstly, in order to figure out whether IL-11 signaling was upregulated in renal fibrosis and its changing trend under osthole treatment." (PMID 34054526, 2021).
renal fibrosis (continued). "IL11 is a close family member of IL6, which was found to be related to he renal fibrosis in our previous studies." (PMID 37853428, 2023). "More importantly, we found that IL-11/ERK1/2 signaling in UUO-induced renal fibrosis and TGF-β-induced HK-2 cell model was obviously upregulated, and osthole treatment also significantly inhibited the abnormal IL-11/ERK1/2 signaling activation." (PMID 34054526, 2021). "Besides, no studies report the pharmacological effects of osthole on the novel therapeutic targets, IL-11/ERK1/2 axis, in renal fibrosis." (PMID 34054526, 2021).
viral infections (12 papers, 2015 to 2024). "Since the nineties, high IL11 release during viral infections have been described, and more recently, several studies have related this interleukin to fibrosis, chronic inflammation and matrix extracellular remodeling." (PMID 37545510, 2023). "Underlying chronic inflammation and/or viral infections create an immune suppressive TME in GC through the production of cytokines including IL-6, IL-11, TNF-α, and transforming growth factor (TGF)-ß35,36." (PMID 37577519, 2023). "Our study is the first to report on the notable and previously unappreciated role of IL-11 in protecting the intestine against viral infection, which broadens our knowledge of the function of IL-11." (PMID 31864417, 2019). "IL-11 is an anti-inflammatory factor, and its expression becomes elevated by virus infection and could be a potential target for novel antiviral development." (PMID 38257829, 2024). "IL-11 viral infections have previously been related to IL-11 expression." (PMID 36742132, 2023). "Furthermore, pIL-11 was found to inhibit viral infection by preventing PEDV-mediated apoptosis of cells by activating the IL-11/STAT3 signaling pathway." (PMID 31864417, 2019). "However, further studies are required to better understand the complex IL-11-related regulatory mechanisms of the antiviral host response during viral infection." (PMID 31864417, 2019). "Therefore, we sought to determine the biological function of IL-11 during viral infection." (PMID 31864417, 2019). "However, little is known of the role of IL-11 during viral infections." (PMID 31864417, 2019). "Pretreatment with recombinant porcine IL-11 (pIL-11) was found to suppress PEDV replication in Vero E6 cells, while IL-11 knockdown promoted viral infection." (PMID 31864417, 2019). "IL-11 mRNA levels in PEDV-infected cells were at least sixfold higher compared with that of the controls, which increases along with viral infection, with RNA expression reaching a peak after 24 h and then gradually decreasing." (PMID 31864417, 2019). "Based on the IL-11 mRNA level in PEDV infected cells, the quantity of secreted IL-11 in supernatants show a similar increasing trend after viral infection." (PMID 31864417, 2019). "In order to verify whether IL-11 expression is related with viral infection, PEDV M and IL-11 gene copies in Vero E6 cells and intestinal tissues were compared using the Pearson correlation." (PMID 31864417, 2019). "In response to viral infections, the generation of a pro-inflammatory response includes the activation of numerous transcription factors, including NF-κB, and the secretion of numerous pro-inflammatory cytokines and metabolites, including TGF-β, IL-1, IL-6, IL-11, and TNF-a." (PMID 36677504, 2023). "In this study, IL-11 expression at mRNA and protein levels were found to be high in Vero cells and the jejunum of piglets during porcine epidemic diarrhea virus (PEDV) infection, while IL-11 expression was found to be positively correlated with the level of viral infection." (PMID 31864417, 2019). "However, the function of IL-11 during viral infection has not been previously reported." (PMID 31864417, 2019).
bone metastasis (11 papers, 2015 to 2025). Transfer of a neoplasm from its primary site to bones. "Intriguingly, in contrast to the prognostic significance of miR-124, higher IL-11 expression in metastatic bone tissues was correlated with shorter overall survival for patients with bone metastasis." (PMID 29343249, 2018). "More importantly, survival analysis showed that a lower miR-124 level and higher IL-11 expression in metastatic bone tissues was correlated with shorter overall survival of patients with bone metastasis." (PMID 29343249, 2018). "Nevertheless, the specific clinical significance of miR-124 and IL-11 in bone metastasis was unclear." (PMID 29343249, 2018). "Several bone metastasis-associated genes induced by TGF-β were revealed to be an indirect effect, such as RANKL, RUNX2, CXCR-4, CTGF and IL-11." (PMID 26697526, 2015). "IL-11 or IL-11 NAb were injected intraperitoneally in a bone metastasis model." (PMID 36593458, 2023). "In contrast to miR-124, the progression time in patients with high IL-11 expression was shorter than in those with low IL-11 level, indicating that patients with higher IL-11 expression might develop bone metastasis earlier." (PMID 29343249, 2018). "Thus, IL-11 is a possible target for the therapeutic strategy of bone metastasis." (PMID 37199584, 2023). "The combined overexpression of IL-11 and osteopontin (OPN, a secretory protein that stimulates the adhesion of osteoclasts to the bone matrix), significantly increases the incidence of bone metastasis." (PMID 37199584, 2023). "The IL-11 protein levels in the serum and primary tumors were significantly higher in patients with bone metastasis compared to those without distant metastasis." (PMID 31040267, 2019). "IL-11 is a negative prognostic factor in renal cancer; consistently, we observed that IL-11 levels were higher in sera of mice with bone metastasis than in non-bone metastasis ones." (PMID 27322553, 2016).
craniosynostosis (11 papers, 2013 to 2025). Craniosynostosis is defined as the premature fusion of one or more cranial sutures leading to secondary distortion of skull shape resulting in skull deformities with a variable presentation. "Loss of function (LOF) in IL11RA infers IL11 signaling as important for fertility, fibrosis, inflammation and incompletely penetrant craniosynostosis." (PMID 34239012, 2021). "Here, we demonstrate that mutations in the IL11RA gene cause autosomal recessive Crouzon-like craniosynostosis or syndromic pansynostosis with mild craniofacial phenotype via impaired interleukin-11 mediated signaling, based on mutations in five families." (PMID 24498618, 2013). "Humans with homozygous LOF in IL11 itself have yet to be described but a human mutation in gp130 that causes selective impairment of IL11 signalling has been characterised: this causes variably penetrant craniosynostosis and retained deciduous teeth." (PMID 38054591, 2023). "In a recent study, a biallelic non-synonymous variant in IL6ST (gp130), which results in a loss of IL11-signaling, conferred a craniosynostosis phenotype, which replicated in a mouse model, although again this phenotype is mediated at the membrane receptor level." (PMID 34239012, 2021). "The skeletal phenotype is probably influenced by impaired IL-11 signaling, given that individuals with IL11RA mutations manifest with craniosynostosis and dental malformations." (PMID 40040707, 2025). "Fittingly, humans with bi-allelic LOF mutation in gp130 that affects both IL11 and IL6 signalling present with combined immunodeficiency (IL6/OSM effect) and craniosynostosis (IL11 effect)." (PMID 38054591, 2023). "A similar dissociation is observed in the IL-11RA defect and craniosynostosis, as IL-11 is known to have a stimulatory effect in osteoblasts predicting osteopenia in IL-11RA deficiency, but the opposite turns out to be true." (PMID 29868029, 2018). "In contrast to individuals with partial LOF IL6ST mutations, complete IL11RA deficiency, or STAT3-DN mutations, individuals with IL6ST-DN do not exhibit craniosynostosis, most likely because of remaining functionality in IL-11 signaling." (PMID 40040707, 2025). "Interestingly, until now, only craniosynostosis patients with variants within the IL11RA gene have been described, but no patients with variants in IL11, which encodes the cytokine itself, are known." (PMID 37596289, 2023). "Interestingly, 40-50% of IL-11RA-/- mice exhibited craniosynostosis-like phenotypes and snout deformities, whereas no snout deformities were observed in IL-11-/-mice." (PMID 37199584, 2023). "Considering the skull, mice lacking IL11 do not have craniosynostosis, and have normal long bone mass, suggesting that IL11 is not relevant in bone development —but IL11 may play a key role in bone regeneration." (PMID 37892923, 2023). "However, the craniosynostosis and bone phenotypes seen in Il11RA1 deficient mice are not seen in Il11−/− mice, suggesting that developmental, STAT3-related bone effects are not due to defective IL11 signaling per se and instead, specific to Il11RA1 LOF." (PMID 34239012, 2021).
liver disease (11 papers, 2011 to 2025). "Therapeutically, these insights are relevant, as IL-6 and IL-11 signaling have emerged as promising targets for metabolic-inflammatory liver disease, with IL-11 shown to potentiate matrix deposition and hepatocyte dysfunction under metabolic stress." (PMID 41470883, 2025). "Hepatocyte replication and liver regeneration is inhibited by IL11 and this pathology, related to SNAI1 up-regulation and hepatocyte partial EMT, is of importance for IL11-driven liver disease." (PMID 38054591, 2023). "Of note, a protective contribution of IL-11 in liver diseases has recently been challenged, making the therapeutic application of IL-11 undesirably." (PMID 37061565, 2023). "IL11 is important for fibrosis in non-alcoholic steatohepatitis (NASH) but its role beyond the stroma in liver disease is unclear." (PMID 33397952, 2021). "Blocking IL-11 is considered a promising target for the fight against liver disease, with an established mechanism of action in both acute and chronic liver diseases." (PMID 33579000, 2021). "Interestingly, rhIL11 acts as an inhibitor of mouse IL11 activity and has been administered to patients in clinical trials for liver diseases." (PMID 40789837, 2025). "Moreover, IL11 is a critical driver of cardiovascular fibrosis, lung abnormalities, kidney injury and renal repair, and liver disease." (PMID 37892923, 2023). "Of the experiments showing a beneficial effect of IL11 in liver disease, the 2001 study by Trepicchio that showed a protective effect of rhIl11 in APAP-induced murine liver failure caught our attention, as effects were acute, dose-dependent and we replicated the findings." (PMID 38054591, 2023). "This is important, as therapeutic targeting of IL11 signaling for fibrotic lung and liver diseases is being considered and it may be that targeting the ligand has potential advantages over the receptor." (PMID 34239012, 2021). "Consequently, their roles in liver disease diverge—IL6 supports protection and regeneration, whereas IL11 promotes inflammation and fibrosis." (PMID 41487426, 2025).